OOSP4B (oocyte secreted protein family member 4B)
Gene: Protein-coding gene on chromosome 11 (59,978,020 to 60,031,095, forward strand). Ensembl gene ENSG00000255393.
Subcellular location: Secreted
Gene Ontology:
Cellular component: extracellular region
Homologues: Orthologues: macaque OOSP4B (88% identical), rabbit OOSP4B (55% identical).